SHOX2 (SHOX homeobox 2)
Diseases named in the same sentence as SHOX2 in open-access papers (continued):
Sharing a sentence is not in itself a finding about the gene and the disease.
lung carcinoma (continued). "The short stature homeobox 2 (SHOX2) and septin 9 (SEPT9), for instance, are employed as diagnostic and screening tools for the detection of lung cancer and colorectal cancer." (PMID 27835597, 2016). "SHOX2 methylation level in lymph node tissue obtained by endobrochial ultrasound with transbronchial needle aspiration (EBUS-TBNA) improved endoscopic lung cancer staging with an assay sensitivity and specificity of 94% and 99%, respectively." (PMID 25229548, 2014). "Noteworthy, elevated SHOX2 methylation levels in pleural effusions do not only allow the detection of lung cancer but also the detection of other malignancies, such as breast cancer and gastrointestinal cancers." (PMID 25229548, 2014). "Pleural effusion samples obtained from patients with different malignancies (including lung cancer) showed a shorter overall survival if elevated levels of SHOX2 methylation were detected." (PMID 25229548, 2014). "SHOX2 DNA methylation is another plasma based biomarker that allows for the identification of lung cancer." (PMID 24699908, 2014). "A CE-marked in vitro diagnostic (IVD) test to aid pathologists in the diagnosis of lung cancer based on the SHOX2 DNA methylation biomarker is commercially available in Europe." (PMID 24386354, 2013). "DNA methylation of SHOX2 was suggested to be a biomarker for diagnosis of lung cancer based on bronchial aspirates." (PMID 24367375, 2013). "Although SHOX2 is a validated biomarker in lung cancer, its positivity was low in pleural fluid of lung cancer patients (13%)." (PMID 24386354, 2013). "SHOX2 DNA methylation has been reported to detect lung cancer in bronchial aspirates with a sensitivity of 68–78% and a specificity of 95–96%." (PMID 24386354, 2013). "This concerted effect qualifies SHOX2 DNA methylation as a biomarker for lung cancer diagnosis, especially when sensitive detection is needed, i.e. in bronchial lavage or blood samples." (PMID 21426551, 2011). "SHOX2 DNA methylation has previously been reported to be applicable for the diagnosis of lung cancer based on the analysis of bronchial lavage samples." (PMID 21426551, 2011). "Genomic gain on chromosome 3q, where SHOX2 is located, has been recognized as one of the most prevalent and significant alterations in lung cancer." (PMID 21426551, 2011). "A hypermethylation of the SHOX2 locus in tumor tissue as compared to the matched NAT from the same patient was detected in 96% of tumors from a group of 55 lung cancer patients." (PMID 21426551, 2011). "Genomic gain of chromosome 3q involving the SHOX2 gene has been recognized as one of the most prevalent and significant chromosomal rearrangements in lung cancer." (PMID 21426551, 2011). "In this study, the SHOX2 DNA methylation was quantified in tumor tissues and morphologically normal adjacent tissues from 55 lung cancer patients." (PMID 21426551, 2011). "The tumor-specific hypermethylation of SHOX2 and its frequent gene amplification in lung cancer renders SHOX2 DNA methylation is an attractive biomarker for lung cancer when sensitive detection is desired, i.e. in bronchial lavage specimens." (PMID 21426551, 2011). "This study aimed to show that SHOX2 DNA methylation is a tumor marker in patients with suspected lung cancer by using bronchial fluid aspirated during bronchoscopy." (PMID 21047392, 2010). "Hypermethylation of SHOX2 in bronchial aspirates appears to be a clinically useful tumor marker for identifying subjects with lung carcinoma, especially if histological and cytological findings after bronchoscopy are ambiguous." (PMID 21047392, 2010). "Based on these results, the use of the SHOX2 tumor marker in a confirmatory test for the diagnosis of lung cancer can be expected to identify more than half of the remaining lung cancer patients in this population." (PMID 21047392, 2010).
lung carcinoma (continued). "DNA methylation of SHOX2 was identified as a biomarker capable of differentiating between lung cancer tissues and normal tissues (t-test p-value = 0.0003, Wilcoxon Rank-Sum test p-value = 0.0006)." (PMID 21047392, 2010). "This assay was then used to quantify the SHOX2 DNA methylation in bronchial aspirates from 523 patients to investigate its ability to identify patients with lung cancer in a population of individuals with suspected lung cancer." (PMID 21047392, 2010). "In this study, DNA methylation of SHOX2 was found as a highly accurate tumor marker for identifying patients with lung cancer based on the analysis of bronchial aspirates." (PMID 21047392, 2010). "Hypermethylation of SHOX2 in bronchial aspirates is a sensitive and specific biomarker for identifying subjects with lung carcinoma, especially if histological and cytological findings after bronchoscopy are ambiguous." (PMID 21047392, 2010). "Research on the methylation of the SHOX2 gene indicates a significant elevation in the methylation levels among lung cancer patients, which can be detected through blood samples and thus serve as an early diagnostic marker for asymptomatic high‐risk populations." (PMID 39991629, 2025). "The detection of SHOX2 methylation can potentially identify early-stage lung cancer patients." (PMID 40515636, 2025). "Therefore, comparing with traditional cytology, the combined detection of SHOX2 and RASSF1A methylation improved the diagnostic efficacy of lung cancer." (PMID 40666096, 2025). "S. platensis has been shown to down-regulate the expression of SHOX2 in A549 lung cancer cells, which may contribute to its anti-proliferative effect." (PMID 41203700, 2025). "Aberrant DNA methylation is closely associated with cellular dysfunctions in lung cancer, such as DNA repair (O6 methylguanine DNA methyltransferase, MGMT), cell growth (Short State Homebox2, SHOX2), and cell cycle (cycling dependent kinase inhibitor 2A, CDKN2A)." (PMID 40666096, 2025). "Moreover, we compared the DNA methylation status of 7 genes (TAC1, CDO1, HOXA9, ZFP42, SOX17, RASSF1A and SHOX2) in lung cancer cases from the mass and GGNs groups." (PMID 38315228, 2024). "Following a large literature review, we explored the performance of the DNA methylation of 7 genes including TAC1, CDO1, HOXA9, ZFP42, SOX17, RASSF1A and SHOX2 in the blood cfDNA samples in distinguishing lung cancer from benign nodules and healthy individuals." (PMID 38315228, 2024). "Furthermore, the methylation positive rates of CDO1 and SHOX2 were different between I-IV stages of lung cancer." (PMID 38315228, 2024). "SHOX2, a significant transcriptional regulator in multiple genetic disorders, has been verified to be a powerful biomarker for the evaluation and diagnosis of a wide variety of cancers, including lung cancer." (PMID 37170390, 2023). "For advanced lung cancer, due to the significant copy number variation in SHOX2, increased extracellular methylation SHOX2 DNA could be exploited for diagnosis and prognosis." (PMID 37170390, 2023). "Notably, the combination of cytology and SHOX2 and RASSF1A methylation analysis can significantly improve the diagnostic efficiency as well as the status identification of MRD in lung cancer." (PMID 35651679, 2022). "NPV and PPV values show that the SHOX2, RASSF1A, and PTGER4 methylation detection of plasma could be an effective complementary tool in high-risk lung cancer diagnosis." (PMID 34408226, 2021). "The potential role of SHOX2 in patients with lung cancer may have been explained by many previous studies." (PMID 34262939, 2021). "However, in recent decades, many researchers have found that SHOX2 also plays an important role in multiple cancers, including lung cancer." (PMID 34262939, 2021).
lung carcinoma (continued). "SHOX2 gene promoter hypermethylation is high in serum, broncholavage fluid and pleural effusion of lung cancer patients, which can be used as a biomarker for auxiliary diagnosis of lung cancer." (PMID 34275516, 2021). "The specific role of SHOX2 in lung cancer patients and the molecular mechanism of its action are unknown." (PMID 34262939, 2021). "Finally, potential co-expressed genes and functional networks were analyzed to provide direction for further investigation into the mechanism of how SHOX2 works in lung cancer." (PMID 34262939, 2021). "It is worth noting that there is little research on the potential prognostic influence and molecular mechanism of SHOX2 in lung cancer, especially in non-small-cell lung cancer (NSCLC) [mainly lung adenocarcinoma (LUAD) and lung squamous cell carcinoma (LUSC)]." (PMID 34262939, 2021). "Because of the hypermethylation of SHOX2 in lung cancer, methylation detection has been applied to assist in the early diagnosis of unknown pulmonary nodules." (PMID 34262939, 2021). "From the tumors with highest incidence, we can stress the relevance of DNA methylation changes in the following genes found in LB: SHOX2 (for lung cancer); RASSF1A, RARB2, and GSTP1 (for lung, breast, genitourinary and colon cancers); and SEPT9 (for colon cancer)." (PMID 34208598, 2021). "However, there are few studies on the mRNA expression, methylation, and molecular mechanism of SHOX2 in lung cancer." (PMID 34262939, 2021). "Short stature homeobox gene two (SHOX2), ras association domain family 1A (RASSF1A), and prostaglandin E receptor 4 gene (PTGER4) methylation has been separately reported to be highly correlated with lung cancer diagnosis and prognosis." (PMID 34408226, 2021). "Interestingly, methylation detection of SHOX2 in sputum, blood, alveolar lavage fluid, and tissue of patients has been used to screen early lung cancer patients." (PMID 34262939, 2021). "Similarly, SHOX2 can be used not only as a marker for early detection of lung cancer, but also as an independent predictor of prognosis for NSCLC5." (PMID 32444802, 2020). "Additionally, other clinical applications such as the assessment of lung cancer stages by measuring the SHOX2 methylation levels of lymph nodes and its efficiency for monitoring the response to chemotherapy have been studied." (PMID 31888670, 2019). "Therefore, the DNA methylation of the SHOX2 gene has been qualified as a sensitive biomarker for lung cancer diagnosis and staging, specifically for SCC and SCLC, accompanied by an analysis of the methylation level of PTGER4 in our study." (PMID 31888670, 2019). "However, the results with regard to the methylation levels of the P16, RASSF1A, APC and SHOX2 genes in lung cancer and controls are still controversial and varied." (PMID 28977861, 2017). "Our findings suggest that methylated SHOX2 gene could be a specific and potential noninvasive biomarker using bronchial aspirates for lung cancer diagnosis, especially for SCC." (PMID 28977861, 2017). "We found that the methylation status of the cyclin-dependent kinase inhibitor 2A (P16), Ras association domain family 1 isoform (RASSF1A), adenomatous polyposis coli (APC) and short stature homeobox 2 (SHOX2) genes was significantly correlated with lung cancer in bronchial aspirates." (PMID 28977861, 2017). "The SHOX2 methylation may become a useful noninvasive biomarker for lung cancer diagnosis, but P16, RASSF1A and APC methylation showed poor diagnostic effects." (PMID 28977861, 2017). "Furthermore, SHOX2 DNA methylation is a validated biomarker for detecting lung cancer in the cellular fraction of bronchial aspirates and pleural effusions as well as in EBUS-TBNA (endobronchial ultrasound with transbronchial needle aspiration) specimens." (PMID 24699908, 2014). "SHOX2 for example is methylated in the different histological subtypes of lung cancer." (PMID 24386354, 2013).
lung carcinoma (continued). "Furthermore, SHOX2 DNA methylation in plasma is a sensitive and specific biomarker for detecting lung cancer." (PMID 24386354, 2013). "DNA methylation in the SHOX2 locus was previously used to reliably detect lung cancer in a group of critical controls, including 'cytologically negative' samples with no visible tumor cell content, at a high specificity based on the analysis of bronchial lavage samples." (PMID 21426551, 2011). "This study sought to assess the aberrant methylation of SHOX2 and RASSF1A in broncho-exfoliated cells (BEC) and compare it with conventional cytology, histology examination, immunohistochemistry, and serum tumor markers to evaluate the overall diagnostic efficiency for lung cancer." (PMID 38429660, 2024). "For example, the DNA locus’s hypermethylation of SHOX2 may serve as a biomarker for lung cancer." (PMID 37170390, 2023). "Furthermore, combination studies to test potential synergistic effects among BCAT1 and other lung cancer biomarkers, such as SHOX2, PTEGR4, could also be considered." (PMID 36123616, 2022). "SHOX2 and RASSF1A methylation tests have diagnostic specificity and sensitivity in peripheral blood, alveolar lavage fluid, and tissue biopsy from lung cancer patients, but their potential for screening and diagnosis of patients with early LUAD remains unclear." (PMID 35837113, 2022). "As reported in detail in our previous review, we synthesized the results of existing studies on SHOX2 and its related homonymous genes in mice, lung cancer and other tumors and concluded that SHOX2 might play an important role in tumorigenesis, metastasis, and recurrence in lung cancer." (PMID 34262939, 2021). "The data showed that the SHOX2 and RASSF1A methylation panel in bronchoalveolar lavage fluid (BALF) yielded a diagnostic sensitivity of 81.0% and specificity of 97.4% with an AUC value of 0.892 in lung cancer diagnosis, but it was showed a lower sensitivity in adenocarcinoma of 69.6%34." (PMID 34408226, 2021). "The most widely used lung cancer-specific gene methylation detection kit is the human SHOX2 and RASSF1A gene methylation DNA detection kit, which could assist in the early diagnosis of lung cancer and in the differentiation between benign and malignant pulmonary nodules." (PMID 32695166, 2020). "Moreover, in the comparison of NSCLC and SCLC, the methylation status of the SHOX2 gene was correlated with lung cancer histology, indicating that the SHOX2 methylation could contribute to the distinction between NSCLC and SCLC." (PMID 28977861, 2017). "Recently, increased SHOX2 methylation levels were also detected in metastatic lymph node tissue obtained by endobronchial ultrasound with transbronchial needle aspiration (EBUS-TBNA) performed in patients with lung cancer, further improving the assessment of nodal status and staging in this entity." (PMID 27999621, 2016). "Indeed, a correlation between SHOX2 methylation and amplification was shown in lung cancer tumors." (PMID 26937257, 2016). "Thus, SHOX2 hypermethylation in lung cancer might be indicative of an overall hypomethylation of the corresponding chromosomal region and therefore of genetic instability which results in gene amplification." (PMID 21426551, 2011). "SHOX2 DNA methylation, operating as a biomarker at a high specificity and sensitivity in a group of lung cancer patients and critical controls based on the analysis of bronchial lavage samples, has recently been proven to be a suitable means for diagnosing lung cancer." (PMID 21426551, 2011). "SHOX2 DNA methylation was shown to reliably detect cancer patients at high specificity in a group of patients with benign lung diseases, i.e. abscesses, infections, obstructive lung diseases, sarcoidosis, scleroderma and stenoses, who underwent the same clinical workup for suspected lung cancer." (PMID 21047392, 2010).
lung carcinoma (continued). "Biomarkers of DNA methylation such as SHOX2, RASSF1A and PTGER4 can be detected during the early stages of lung cancer, achieving both high sensitivity and specificity." (PMID 40666096, 2025). "A validation study demonstrated that the combined SHOX2 and PTGER4 methylation assay is capable of effectively distinguishing lung cancer patients from healthy individuals." (PMID 40666096, 2025). "The current results showed that S. platensis down-regulated the expression of SHOX2 and up-regulated the expression of BRMS1 in A549 lung cancer cells." (PMID 41203700, 2025). "Some methylation markers, such as SHOX2, RASSF1A, APC, etc., can be detected in the early stage of lung cancer, with both sensitivity and specificity reaching a relatively high level." (PMID 40666096, 2025). "Methylation of the promoters of SHOX2 and RASSF1A (LungMe®) exhibits promise as a potential molecular biomarker for diagnosing lung cancer." (PMID 38429660, 2024). "The combined analysis of SHOX2 and RASSF1A methylation serves as a powerful complement and extension to conventional methods, enhancing the accuracy of a lung cancer diagnosis with satisfactory sensitivity and specificity." (PMID 38429660, 2024). "The results demonstrated that, at a fixed specificity of 90%, the sensitivity of SHOX2 and PTGER4 methylation in plasma for lung cancer was 67%." (PMID 38429660, 2024). "The combination detection of SHOX2 and RASSF1A methylation has been utilized in diagnosing lung cancer, with a sensitivity of 71.5–96.0%, and a specificity of 82.3–100%." (PMID 38840077, 2024). "SHOX2 and RASSF1A methylation have been identified as important biomarkers for diagnosis and prognosis of lung cancer." (PMID 38996143, 2024). "The utilization of SHOX2 and RASSF1A methylation has been shown to enhance the sensitivity of early lung cancer detection, as substantiated by multiple scholarly literature." (PMID 38840077, 2024). "The aim of this study is to diagnose lung adenocarcinoma by measuring the methylation levels of SHOX2 and RASSF1A, and provide an accurate pathological diagnosis to predict the invasiveness of lung cancer prior to surgery." (PMID 38840077, 2024). "In our study cohort, lung cancer (nonsmall-cell lung cancer, NSCLC and small cell lung cancer, SCLC) accounted for the largest proportion of MPE, and the sensitivity of SHOX2, RASSF1A, and TM were 91.1% (41/45), 64.4% (29/45), and 97.8% (44/45), respectively." (PMID 36691467, 2023). "There have also been studies about the distribution of the methylation status of SHOX2 and RASSF1A in different lung cancer subtypes using bronchial aspirates and FFPE samples." (PMID 36691467, 2023). "The detection sensitivities of SHOX2, RASSF1A, and TM in lung cancer-derived MPE were 91.1%, 64.4%, and 97.8%, slightly higher than those in the overall MPE samples." (PMID 36691467, 2023). "ETCs counting in combination with SHOX2 and RASSF1A methylation assays in BALF samples has demonstrated excellent sensitivity for lung cancer diagnosis and is an effective complementary tool for clinical diagnosis of lung cancer." (PMID 37682182, 2023). "Our data showed that the sensitivity of SHOX2 and RASSF1A methylation in lung cancer diagnosis was 72.8%, the specificity was 87.1%, and the AUC value was 0.800." (PMID 37182143, 2023). "ETCs counting in combination with SHOX2 and RASSF1A methylation assays in BALF has shown to be highly efficient in lung cancer diagnosis and is an effective complementary tool for clinical diagnosis of lung cancer." (PMID 37682182, 2023). "In conclusion, SHOX2 and RASSF1A methylation detection in BFF/BALF can be used to diagnose lung cancer." (PMID 37182143, 2023). "The results showed that the sensitivity of SHOX2 and RASSF1A methylation detection in the lung cancer and control groups was 72.8% and 12.9%, respectively." (PMID 37182143, 2023).